ZEB2 (zinc finger E-box binding homeobox 2)
Diseases named in the same sentence as ZEB2 in open-access papers (continued):
Sharing a sentence is not in itself a finding about the gene and the disease.
tumor (continued). "ZEB1 and ZEB2 are EMT-associated transcription factors involved in tumor metastasis." (PMID 34226299, 2021). "It is plausible that smoking-associated disruption of ZEB2 regulatory activity could skew lung alveolar macrophage polarization to an inflammatory phenotype that promotes tumor development." (PMID 32963246, 2020). "Thus, potent EMT inducers, including Snail, Slug, Twist, and ZEB2, have been implicated in tumor progression and metastasis." (PMID 31831830, 2019). "Furthermore, the members of the miR-200 family together with miR-205 regulate the expression of target genes ZEB1 and ZEB2, which have been implicated to be involved in epithelial to mesenchymal transition and tumor progression." (PMID 25889518, 2015). "To evaluate the effect of miR-200 and Zeb2 on tumor formation and metastasis, we next engineered retroviruses encoding the miR-141-200c cluster mature miRNAs or control virus expressing firefly luciferase shRNA or Zeb2 shRNA within the miR-30 stem." (PMID 19787069, 2009). "In contrast, in a recent report depicting six master regulators (AEBP1, HOPX, PRRX1, SNAI2, ZEB1, ZEB2) of the TCGA “mesenchymal” subtype, they employed a network-based strategy to uncover the molecular mechanism underlying the discrete mesenchymal subtype in whole tumor tissues of serous OC." (PMID 27081703, 2016). "Yet the detailed mechanisms connecting ZEB2 to tumor evolution and therapy resistance, particularly its influence on the tumor microenvironment (TME), remained unresolved in NSCLC." (PMID 40510028, 2025). "Regarding our findings, several hub genes, including ADAM12, MET, THBS2, ZEB1, and ZEB2, have been previously implicated in PDAC progression, tumor invasiveness, and epithelial–mesenchymal transition (EMT)." (PMID 40728965, 2025). "MEF2A transcriptionally upregulates the expression levels of catenin beta 1 (CTNNB1) and zinc finger E-box binding homeobox 2 (ZEB2) in CRC to promote tumor progression." (PMID 40592832, 2025). "Using qRT-PCR, we observed a decrease in E-cadherin and an increase in mesenchymal markers such as Slug, N-cadherin, vimentin, ZEB1, and ZEB2 in LNCaP cells treated with periprostatic tumor fat medium, indicating epithelial–mesenchymal transition." (PMID 40437336, 2025). "In conclusion, our findings highlight a previously unrecognized role of the transcription factor ZEB2 in supporting lung tumor-reactive Teff cell differentiation and the anti-tumor efficacy of CD8+ TILs in NSCLC." (PMID 41203628, 2025). "By targeting ZEB1 and ZEB2, miR-200c promotes the maintenance of epithelial characteristics in cells, thereby acting as a tumor suppressor." (PMID 39859424, 2025). "Analyzing by tissue distribution, the gene expression levels of ZEB2 and TBX21 as well as ZEB2 transcriptional activity were downregulated in the tumor environment relative to the adjacent normal tissue and peripheral blood." (PMID 41203628, 2025). "Here, we concentrated on EGFR-TKI-resistant NSCLC to delineate how ZEB2 remodeled the TME, with emphasis on tumor-associated macrophage (TAM) dynamics." (PMID 40510028, 2025). "In both KP.SIY models, Zeb2 knockout significantly suppressed the proportion of lung tumor-reactive Teff cells in the spleen on day 7 post-tumor cell inoculation." (PMID 41203628, 2025). "In our research, the expression of ZEB2 was increased in both EGFR-TKI-resistant NSCLC tumor cells and EGFR-TKI-resistant patients’ samples." (PMID 40510028, 2025). "This transition occurs through the action of transcriptional factors such as Slug and ZEB2, ultimately promoting tumor invasion and metastases via EMT." (PMID 39516342, 2024). "As illustrated in the MM10 tumor, which bore the presence of a well-defined ZEB1high clone, increased ZEB1 expression was not only associated with low ZEB2 and MITF expression, but also with decreased SOX10 levels." (PMID 38519642, 2024).
tumor (continued). "Using previously reported signatures, we found that 3 weeks after chronic tumor-antigen stimulation, multiple T-bet-repressed/ZEB2-dependent MP genes, as well as T-bet-induced/ZEB2-independent TE genes, were significantly higher expressed in Ctbp1-KO cells." (PMID 38490212, 2024). "The miR-18a/low tumours segregated based on the lower quartiles of miR-18a expression were found to express high levels of ZEB2 (p = 0.05) as assessed by q-PCR." (PMID 38786043, 2024). "The elevated LDHA can promote EMT of tumor cells through upregulating the expression of ZEB2 and activating of TGF‐β due to the low extracellular pH induced by the secretion of lactate." (PMID 39092293, 2024). "Hypoxia in the TME can induce high levels of diacylglycerol kinase gamma in tumor vascular endothelial cells, which in turn can promote tumor angiogenesis and immune evasion in hepatocellular carcinoma through the ZEB2/TGF-β1 axis." (PMID 39588373, 2024). "For instance, ZEB2, a transcription factor essential for NK cell maturation and a key player in tumor cytotoxicity, showed increased expression." (PMID 39445004, 2024). "The CAF Meg3 cluster exhibited an almost threefold increase in dKO tumours, and with NC Zeb2, this cluster was the most relatively enriched cell type." (PMID 37605008, 2023). "Thereby, high ZEB2 and low ZEB1 expression levels were associated with primary tumor growth, differentiation, metastatic outgrowth and survival." (PMID 38139138, 2023). "By contrast, comparable ZEB2 expression levels were observed in the M13HS-2 and -8 tumor hybrids and their ZEB1-KO variants." (PMID 38139138, 2023). "The results showed that silencing of RSPH14 partially reversed the enhanced effect of tumor growth induced by knocking down lnc-ZEB2-19." (PMID 37564197, 2023). "Several factors mediate ZEBs; for example, the activation of MEK1/2, ERK1/2, Fos-related antigen 1 (Fra-1), and TGF-β enhance the expression of both ZEB1 and ZEB2, increasing tumor invasion." (PMID 37444447, 2023). "Multiple cancer types, including OC, breast, hepatocellular, colorectal, and gastric cancer with overexpression of ZEB2 revealed a correlation with tumor metastasis, progression of the disease, and poor prognosis." (PMID 37174083, 2023). "ZEB2 belongs to the zinc finger homeobox protein family that regulates the tumor progression and chemotherapy response." (PMID 37480054, 2023). "Mechanistically, lnc-ZEB2-19, as a tumor suppressor gene, inhibits the activation of NF-kappa B by interacting with TRA2A to decrease the stabilization of RSPH14 mRNA." (PMID 37564197, 2023). "Among these miR genes, Zeb2 binds to loci encoding miR-144, miR-148a, miR-9, and miR-153, known to target Zeb2 in the context of e.g., tumor EMT and tumor progression." (PMID 36980900, 2023). "Many of the DEGs were involved in ferroptosis (Ptgs2), enhanced T-cell function (Lef1), regulators of EMT (Zeb1, Zeb2, Vimentin, and Sfrp2), and fibrosis (Col1α1 and Acta2) in the tumor microenvironment." (PMID 36835036, 2023). "Similar to in vitro data, we found that BATF2-KD tumor-bearing mice had upregulated expression levels of PD-L1, ZEB2, and p-AKT–PI3K." (PMID 37777155, 2023). "High expression of LINC01296 in CRC and NSCLC cells upregulates ZEB1/ZEB2 by acting as miR-141-3p sponge to promote tumor EMT, invasion, and migration." (PMID 37511619, 2023). "The RUV-III normalization revealed that high expression of the ZEB2 gene is associated with a poor outcome in the TCGA BRCA RNA-seq data, but this was obscured by variation in tumor purity in the FPKM.UQ normalized data." (PMID 36109686, 2023). "Two TS-SLC genes, SLC29A1 (ENT1) and SLC8A1 (NCX1), are downregulated in tumor cells (TCS) via the EMT-induced zinc finger E box binding homology box 2 (ZEB2)/transforming growth factor (TGF)-BR/nuclear factor (NF)-kB pathway, or miR-223 in HCC, respectively." (PMID 36844876, 2023).
tumor (continued). "The transcription factors ZEB1 and ZEB2 are significantly downregulated in all cell lines compared to tumor tissue." (PMID 37345150, 2023). "Relative to the total, dKO tumours were enriched in NC Zeb2 cells to the detriment of NC arrested and Hapln1 cells." (PMID 37605008, 2023). "ZEB2 is a DNA-binding transcription factor; previous studies have shown that ZEB2 can induce tumor cells to express PD-L1 and then escape immune surveillance." (PMID 37777155, 2023). "It has been found that short hairpin silencing of LARP7 in MCF10A cells can upregulate the expression levels of P-TEFb-mediated EMT and metastatic genes (such as Slug, Twist1 and ZEB2), thereby promoting tumor invasion and metastasis." (PMID 36052258, 2022). "The Tumor Immune Estimation Resource was used to investigate the correlation between ZEB2 and infiltrating immune cells in various cancers, including OV." (PMID 35723302, 2022). "Zeb2 has extensively been studied in cancer because of its role in primary tumours and metastasis by promoting EMT." (PMID 33909875, 2022). "ZEB2 and Vimentin staining in L6 were clearly located in tumor pseudocrypts, further supporting a more pronounced EMT state of tumor cells." (PMID 35837106, 2022). "The miR-141/ZEB2 axis produces anti-tumor effects and regulates EMT and CSC to significantly inhibit renal cell carcinoma." (PMID 36686745, 2022). "The results of the in vivo experiment showed that LINC00847 knockdown suppressed TU212 cell xenograft tumor growth in nude mice, while overexpression of ZEB2 counteracted this effect." (PMID 35435130, 2022). "The expressed ZEB2 in tumours is involved in the cell cycle, apoptosis, unregulated cell proliferation, EMT and cancer development and progression." (PMID 36499447, 2022). "Due to the demethylation activity of TET1, its knockdown results in the up-regulation of ZEB2 expression as well as in up-modulation of the methylation level of the ZEB2 promoter, allowing promotion of malignant progression in tumor cells." (PMID 36140539, 2022). "In vitro studies showed that circNUP214 induced tumor cell migration and invasion through miR-145 sponging, releasing the inhibitory effect on zinc finger E-box binding homeobox (ZEB2)." (PMID 36077665, 2022). "These regulators jointly suppressed the expression level of the ZEB2 gene, which leads to the suppression of the proliferation and migration of tumor cells." (PMID 36362406, 2022). "First, we observed downregulation of miR-200b, PTPN13 and ZEB2 in CRC with serosal invasion (pT4a) compared to pT3 tumours." (PMID 36140249, 2022). "ZEB2 plays a significant role in EMT during tumor invasion and metastasis in a variety of human malignancies." (PMID 35723302, 2022). "According to published studies, EMT is an essential mechanism for tumor progression, intrusion, and metastasis, and ZEB2 has been reported as a key transcription factor for EMT." (PMID 35723302, 2022). "RT-PCR analysis of EMT-associated factors showed that the orthotopic tumor had an increased expression of EMT-associated factors Vimentin, Twist, ZEB1, SNAIL and ZEB2 as compared to metastatic tissues." (PMID 35837106, 2022). "In gastric MALT lymphoma cells, miR-383 inhibited cell division by inhibiting ZEB2 expression and acted as a tumor suppressor." (PMID 36313570, 2022). "In subcutaneous xenotransplanted tumor model, compared with the control group, the tumor volume of the mice was markedly decreased after knockdown of circ_0000189 or ZEB2, but the tumor volume was increased after circ_0000189 overexpression." (PMID 36193069, 2022). "The sequence of miR-203a-3p is complementary to conservative sites of 3′-UTRs of ZEB1 and ZEB2 that suggests miR-203a-3p to be a tumor suppressor." (PMID 35163224, 2022). "The tumor-infiltrating lymphocytes positively correlated with the expression of ZEB2 but negatively correlated with the methylation of ZEB2." (PMID 36072677, 2022).
tumor (continued). "Western blot showed that compared with the control group, ZEB2 expression was declined in tumor tissues after circ_0000189 or ZEB2 was knocked down, but ZEB2 expression was increased in tumor tissues after circ_0000189 overexpression." (PMID 36193069, 2022). "A recent study revealed that ZEB2 also influenced immune infiltration in the tumor microenvironment." (PMID 35592316, 2022). "TMPRSS4 is a serine protease associated with tumor cells migration and adhesion by EMT promotion through SIP1/ZEB2 induction." (PMID 35659780, 2022). "Expression of both ZEB1 and ZEB2 was differential in OvCa samples (TCGA vs. GEO, p < 0.05) and present in all analyzed tumor and normal tissues." (PMID 35163224, 2022). "Nuclear ZEB2 was observed in 87% (26/30) of the primary CRC tumours and 83% (25/30) of the paired liver metastases." (PMID 33931939, 2021). "ZEB1 and ZEB2 are EMT transcription factors which synergistically increase tumor invasion and cell migration." (PMID 34201896, 2021). "MiR-335 acted also as a tumor suppressor by targeting the zinc finger E-box binding homeobox 2 (ZEB2)." (PMID 35186709, 2021). "In AML, the GSK2879552 therapeutic strategy extinguishes the interaction of ZEB2-KDM1A targeting cells with high ZEB2 levels, inhibits tumor invasion and growth, and then affects tumor survival." (PMID 34001246, 2021). "We observed that the PRRX1-high tumours expressed several cancer-associated genes (e.g. MMP2/9, ZEB2, VIM)." (PMID 34496784, 2021). "Among them, cyclin-dependent kinase 6 (CDK6) and ZEB1/ZEB2 were essential regulators in cell cycle and metastasis of tumor cells, respectively." (PMID 34796112, 2021). "An immunohistochemistry study on ZEB2 expression in 116 RCC patients demonstrated high ZEB2 expression in RCC tumours that correlated with poor overall survival (OS) and progression-free survival (PFS) in RCC patients." (PMID 34099013, 2021). "In searching for the key transcript regulating EOC-CSLC-initiated peritoneal metastasis, we found that the difference in ZEB2 between ascites and primary tumours was more distinguishing than that of other transcripts." (PMID 34211089, 2021). "Based on the information from public database, we assure that ZEB2 exerts its tumor-promoting effects in NSCLC." (PMID 34107856, 2021). "More than 96% (25/26) of ZEB2‐positive primary tumours also stained positive for ZEB2 in their corresponding liver metastases." (PMID 33931939, 2021). "Taken together, analysis of data in this study evidenced that miR-6734-3p served as a tumor suppresser to hinder NSCLC progression by degrading ZEB2 mRNA." (PMID 34107856, 2021). "Top upregulated master regulators in the tumor, as compared to the parent cells, include ZEB2 and PHLDA1; while top downregulated master regulators include AR, AHR, and ITGA6." (PMID 33808801, 2021). "Previous studies have reported that ZEB2 plays an important regulatory role in the process of tumor metastasis." (PMID 34551777, 2021). "We found that circVAPA and ZEB2 mRNA expression was downregulated while the miR-342-3p level was upregulated in xenograft tumor tissues in the sh-circVAPA group compared with the sh-NC group." (PMID 34839824, 2021). "Patients with high expression of ZEB2 in tumour tissues had a higher metastasis rate and a poorer prognosis than those with low expression." (PMID 34211089, 2021). "Through the ceRNA network, UCA1 can regulate the expression of miR-203-targeted transcript ZEB2 that is a transcription factor related to tumor metastasis." (PMID 34464437, 2021). "Although both IL-6 and HGF activate STAT3 and induce ZEB2, they seem to play a different role in tumor progression." (PMID 34408135, 2021). "ZEB2 expression in primary tumours was an independent prognostic marker of reduced overall survival and disease‐free survival in patients who received adjuvant FOLFOX chemotherapy." (PMID 33931939, 2021).
tumor (continued). "Although ZEB2 was detectable in tumor samples, it was at below the limit of detection in cultured cells; therefore we were unable to test the effects of various conditions on ZEB2 in the cell study." (PMID 33808801, 2021). "Accordingly, in a SMAD4/7 knock-out mouse model, SMAD4 was required for tumor formation, and a low level of SMAD7 expression promoted an invasive phenotype and metastatic spread associated with ZEB2/ZEB1 switching." (PMID 32759677, 2020). "Reduced miR-205-5p expression triggers the induction of ZEB2, which in turn enhances the migration ability of tumor cells." (PMID 32664703, 2020). "Results indicated that hsa_circ_0136666 and ZEB2 expressions were decreased in tumor tissues of si-circ group while miR-593-3p level was increased, indicating that hsa_circ_0136666/miR-593-3p/ZEB2 axis contributes to OS growth in vivo." (PMID 32424109, 2020). "MiR-138-5p uses a same strategy in inhibition of lung adenocarcinoma cell malignancy, by suppressing EMT through ZEB2 inhibition to attenuate metastasis of tumor cells." (PMID 32664703, 2020). "LncRNA UCA1 enhances the progression and metastasis of tumor cells through disrupting the miR-203/ZEB2 axis." (PMID 32664703, 2020). "MAGI2-AS3 was identified as an EMT-related lncRNA and is highly co-expressed with ZEB1 and ZEB2 in both tumor and normal stomach tissues." (PMID 32987716, 2020). "The miR-200 family, composed of miR-200a, miR-200b, miR-200c, miR-141 and miR-429, mainly inhibits EMT by targeting the 3 'UTRS of ZEB1 and ZEB2 to inhibit tumor invasion and metastasis 5, which is considered as a tumor suppressor miRNA." (PMID 32226520, 2020). "Altogether, these results identify ZEB2/pCRAF/pASK1 as factors present in rare quiescent cells in untreated tumors that are largely expressed upon chemotherapy treatment, thus inducing tumor transition towards an EMT/chemotherapy unresponsive state." (PMID 31910865, 2020). "In TNBC cells, miR-124 effectively decreases the malignancy and invasion of tumor cells by EMT inhibition through ZEB2 down-regulation." (PMID 32664703, 2020). "As such, ZEB1 and ZEB2 are mainly considered as drivers of tumour cell invasion into distant tissues." (PMID 32796736, 2020). "Aside from that, it has been reported that miR-145 represses EMT, tumor migration, and invasion by directly targeting the 3’-UTRs of ZEB2 in the tumor." (PMID 32850817, 2020). "Specifically, by targeting human epidermal growth factor receptor 3 (HER3), miR-205 inhibits cell proliferation and migration and, by repressing ZEB1 and ZEB2, it limits tumor invasion." (PMID 33191398, 2020). "Among these, TGFβ2 was identified as crucial for the induction of dormancy in disseminated tumor cells and emerged as highly upregulated in ZEB2-overexpressing tumors." (PMID 31910865, 2020). "We confirmed the enrichment of ZEB2 mRNA in PKH26+ cells isolated ex vivo from tumor xenografts and in chemotherapy-treated cells, while in xenograft sections ZEB2-expressing areas overlapped with PKH26+ areas." (PMID 31910865, 2020). "In this context, cytoplasmic YB-1 has been shown to promote the translation of mRNAs encoding both epithelial-to-mesenchymal transition (EMT)-regulating (e.g., Snail, Twist, Zeb2/Sip1) and cytoprotective factors facilitating tumour cell metastasis." (PMID 32824741, 2020). "The miR‐200 family was found to act as a tumor‐suppressive group of miRNAs that targets ZEB1, ZEB2, and Slug genes, which drive epithelial–mesenchymal-transition and tumor progression in prostate cancer cells." (PMID 31866857, 2019). "That fibroblasts and tumour cells appeared to be able to interact and crosstalk reciprocally, we investigated the effect of CAFs and normal human fibroblasts (NFs) on ZEB2-mediated drug resistance of CRC cells." (PMID 30783098, 2019). "ZEB2 exhibits a considerable level in various human tumor tissues, including NSCLC, HCC and gastric cancer." (PMID 30979827, 2019).